EZH2 (enhancer of zeste 2 polycomb repressive complex 2 subunit)
Diseases named in the same sentence as EZH2 in open-access papers (continued):
Sharing a sentence is not in itself a finding about the gene and the disease.
myelodysplastic syndrome (60 papers, 2011 to 2025). A clonal hematopoietic disorder characterized by dysplasia and ineffective hematopoiesis in one or more of the hematopoietic cell lines. "EZH2 loss-of-function mutations are common in patients with myelodysplastic/myeloproliferative neoplasms, myelodysplastic syndrome, and myelofibrosis." (PMID 40700255, 2025). "EZH2 gene mutations are found in myelodysplastic syndrome (MDS), lymphoma, colorectal cancer, and endometrial cancer." (PMID 38773600, 2024). "Point mutations within the D2, CXC, and SET domains of EZH2, including D664A and A255T in myelodysplastic syndrome and G266E, T393M, E549X, C606Y, and P577L in T-ALL, have been identified." (PMID 38036730, 2023). "While loss-of-function mutations of EZH2 frequently affect patients with myelodysplastic/myeloproliferative neoplasms, myelodysplastic syndrome and myelofibrosis, cases of chronic myeloid leukemia (CML) seem to be largely characterized by EZH2 overexpression." (PMID 32650416, 2020). "Recent data suggest that EZH2 loss is more strongly associated with myelodysplastic syndromes, particularly, chronic myelomonocytic leukemia." (PMID 27793053, 2016). "In myeloid neoplasms, EZH2 mutations were identified in 10–13% of poor-prognosis myelodysplastic syndromes-myeloproliferative neoplasms, 6% of myelodysplastic syndromes, 6% of chronic myelomonocytic leukemia, and 1.7% of AML." (PMID 25955299, 2015). "Loss of heterozygosity affecting these two chromosomes and mutations in TET2 and EZH2 are indicative of a myelodysplastic syndrome with a poor prognosis." (PMID 25177364, 2014). "Inactivating mutations in the EZH2 gene in myelodysplastic syndromes are frequent and point to a general function of EZH2 as a tumor suppressor." (PMID 23077658, 2012). "EZH2 inactivating deletions, frameshift, and nonsense and missense mutations have been identified in parts of T-cell acute lymphocytic leukemia, myeloproliferative neoplasms, and myelodysplastic syndromes." (PMID 33163485, 2020). "Inactivating somatic EZH2 mutations have been reported in myeloid neoplasms such as poor prognosis myelodysplasia-myeloproliferative neoplasms (10-13%), myelofibrosis (13%) and various subtypes of myelodysplastic syndromes (6%)." (PMID 22190405, 2011). "However, in some cancers like myelodysplastic syndrome, mutational inactivation of EZH2 is linked to a bad prognosis, indicating that the function of EZH2 in cancer may be cell-context dependent." (PMID 30619733, 2018). "In the fourth research field, which included transcription regulation, curcumin was found to produce a reduction of the expression of the histone methyltransferase EZH2 in a xenograft mouse model of myelodysplastic syndrome." (PMID 37376060, 2023). "For example, mutation of SRSF2 alters its RNA-binding recognition and thereby promotes mis-splicing and NMD of EZH2, results in impaired hematopoietic differentiation in myelodysplastic syndromes (MDS) development." (PMID 35379802, 2022). "Even though EZH2 overexpression and gain-of-function present oncogenic activity, EZH2 also plays a crucial role in tumor suppression, such as myelodysplastic syndromes, myeloproliferative neoplasms, and T cell acute lymphoblastic leukemia." (PMID 36276954, 2022). "EZH2 inactivating mutations have been reported in myeloid hemopathies including chronic myelomonocytic leukemia (CML), myelofibrosis, myelodysplastic syndrome (MDS) and AML." (PMID 34202528, 2021). "Finally, patients with myelodysplastic syndromes (MDS) presenting with monosomy 7 (where EZH2 is located) or inactivating point mutations of EZH2 respond better to treatment with 5‐azacytidine, suggesting that dual inhibition of EZH2 and DNA methylation might be more effective in these patients." (PMID 29130642, 2018).
myelodysplastic syndrome (continued). "In myelodysplastic syndromes and in clonal hematopoiesis (CHIP), EZH2 and TET2 have been reported to be associated with higher rate of cardio-vascular events, and TET2 mutations (at low allelic burden) seem to positively predict the response to azacitidine." (PMID 30574454, 2018). "While EZH2 mutations have been described in approximately 2% of de novo acute leukemia, genomic loss of EZH2 can lead to epigenetic changes and overexpression of the HOX genes in myelodysplastic syndrome." (PMID 28918518, 2017). "However, there are also reports of myelodysplastic syndromes (MDS) exhibiting mutations that inactivate EZH2, hence highlighting EZH2’s potential to act as a tumor suppressor under certain cellular conditions." (PMID 39655332, 2024). "A study examining the impact of inactivating Ezh2 mutations in myeloid malignancies in mice reported that mice developed myelodysplastic disorders that were transplantable and led to the development of myelodysplastic syndrome (MDS), lymphoma, and lymphoproliferative disease." (PMID 38028538, 2023). "However, reducing EZH2 levels has also been shown to have its dangers, as particular myelodysplastic syndromes naturally inactivate EZH2, suggesting a tumor suppressor role for EZH2 in this context." (PMID 27634879, 2016). "Study shows that EZH2 deletion results in myelodysplasia, myelodysplastic syndrome (MDS) and myeloproliferative neoplasms (MPNs) development in mice." (PMID 33759287, 2021). "EZH2 mutation and SETD2 deficiency correlates with poor survival in myelodysplastic syndrome (MDS)." (PMID 36671446, 2022). "Mice with conditional deletions of EZH2 and TET2 in hematopoietic stem cells develop myelodysplastic syndrome and myeloproliferative neoplasms." (PMID 28758948, 2017). "We examined the effect of altered EZH2 levels on H3K27 methylation, HOX gene expression, and malignant phenotype in myelodysplastic syndrome (MDS) cell lines and an in vivo xenograft model." (PMID 26812882, 2016). "For instance, as opposed to its more classical role as an oncogene, EZH2 appears to repress development of myelodysplastic syndrome." (PMID 27634879, 2016). "However, in cases of myelodysplastic syndrome (MDS), myeloproliferative tumor (MPN), and myelodysplastic/myeloproliferative neoplasms (MDS/MPN), it has been found that loss-of-function mutations in EZH2 could lead to the upregulation of certain oncogenic genes." (PMID 32448308, 2020). "LOF(loss-of-function) mutations that disrupt PRC2 activity have been described inall three core components: EZH2, SUZ12, and EED.LOF mutations in EZH2 andEED have been shown to be associated with a negative prognosisin myelodysplastic syndrome/myeloproliferative neoplasm." (PMID 33456979, 2020).
osteosarcoma (59 papers, 2013 to 2025). A usually aggressive malignant bone-forming mesenchymal neoplasm, predominantly affecting adolescents and young adults. "Osteosarcoma cells with high EZH2-linked repression programs co-localize with myeloid niches that display reduced IRF accessibility, indicating convergent dampening of interferon pathways across compartments." (PMID 41383594, 2025). "A study showed that sumoylation of EZH2 is associated with EZH2 activity in U2OS cell (osteosarcoma cell line)." (PMID 33308321, 2020). "Results showed that higher expression of EZH2 was significantly associated with more aggressive tumor behavior and poor patient outcomes of osteosarcoma." (PMID 27223261, 2016). "In this study, we examined EZH2 expression by immunohistochemistry in a large series of osteosarcoma tissues in association with tumor characteristics and patient outcomes." (PMID 27223261, 2016). "The results confirmed that higher EZH2 expression was associated with a poorer prognosis in osteosarcoma." (PMID 27223261, 2016). "In summary, we have provided evidence demonstrating that elevated EZH2 expression in osteosarcoma is significantly associated with tumor metastasis and poor prognosis." (PMID 27223261, 2016). "Immunohistochemical analysis indicated that EZH2 expression was significantly associated with more aggressive tumor behavior and poorer patient outcomes of osteosarcoma." (PMID 27223261, 2016). "In this study, we found that EZH2 was abnormally elevated in osteosarcoma, and its overexpression was associated with poor prognosis in osteosarcoma." (PMID 26265454, 2015). "EZH2 expression is significantly associated with the Enneking stage of osteosarcoma (P < 0.01, Pearson χ2 test), grade and lung metastasis, whereas the results related to sex, age, tumor size, local recurrence and pathological subtypes are negative." (PMID 26265454, 2015). "A major role for EZH2 in tumour cell proliferation and metastasis in cooperation with lncRNAs has been reported in various cancers, though its association with lincFOXF1 in osteosarcoma cells is proposed herein for the first time." (PMID 32945076, 2020). "To further elucidate the molecular mechanisms underlying the effects of EZH2 in osteosarcoma cells, we investigated several apoptotic related proteins after EZH2 silencing and the results showed that several anti-apoptotic proteins were reduced, as well as activation of caspase-3 and PARP cleavage." (PMID 27223261, 2016). "Since the overexpression of EZH2 is associated with more aggressive tumor behavior and poorer patient outcomes in osteosarcoma, we performed a proliferation assay to determine whether EZH2 silencing could inhibit cell growth." (PMID 27223261, 2016). "Dysregulated expression of EZH2 may be involved in the progression of osteosarcoma, and may be a valuable prognostic marker that distinguishes less aggressive osteosarcoma from those at risk of lethal progression." (PMID 27223261, 2016). "Interestingly, while our manuscript was in the preparation, a study reported that overexpression of EZH2 is associated with poor prognosis in osteosarcoma." (PMID 27223261, 2016). "Therefore, the association between EZH2 and human osteosarcoma still warrants further investigation." (PMID 26265454, 2015). "Therefore, the examination of EZH2 expression by IHC could be used as an additional effective tool in identifying those osteosarcoma patients at increased risk of tumor progression and/or metastasis." (PMID 26265454, 2015). "Since the overexpression of EZH2 is associated with a more aggressive osteosarcoma tumor phenotype, we performed a CCK-8 assay, soft agar assay and cell cycle assay to determine whether EZH2 silencing can inhibit cell growth, colony formation and cell cycle arrest of osteosarcoma cells." (PMID 26265454, 2015). "Combining anti-GD2 ADC therapy with EZH2 inhibition effectively improves targeted treatment for osteosarcoma." (PMID 40533837, 2025).
osteosarcoma (continued). "A previous study revealed that circPRDM2 acted as a molecular sponge and abolished miR-760 of targeting EZH2 in osteosarcoma." (PMID 41327336, 2025). "The abnormal differentiation programs of MSCs regulated by EZH2 results in osteosarcomas and chondrosarcomas." (PMID 36622753, 2023). "This regulation of EZH2/SULF1 axis was also observed in the other sarcoma cells such as osteosarcoma cell lines." (PMID 36622753, 2023). "FOXD2-AS1 was found to play a critical role in hypoxia-induced osteosarcoma tumorigenesis by interacting with the EZH2 and repressing p21 protein expression." (PMID 35755302, 2022). "When DANCR was knocked down, it lowered the EZH2 expression and activated both p21 and p27, hence inhibiting the osteosarcoma cell proliferation, migration, and invasion." (PMID 35755302, 2022). "lncRNA HOXD-AS1 epigenetically inhibits p57 by interacting with EZH2, thereby repressing the expression of p57 and aggravating osteosarcoma oncogenesis." (PMID 35755302, 2022). "MALAT1 interaction with the enhancer of zeste homolog 2 (EZH2) suppresses E-cadherin expression, thus promoting osteosarcoma metastasis." (PMID 34791419, 2022). "miR-101 is a well-known tumor suppressor miRNA in several cancers and in osteosarcoma, it was found functioning through repressing EZH2 expression to decrease metastasis." (PMID 35755302, 2022). "Several studies found the interaction between DANCR and EZH2 in many tumor types including osteosarcoma." (PMID 35755302, 2022). "A study has revealed that FOXP4-AS1 is involved in the progression of osteosarcoma through binding to EZH2." (PMID 34545456, 2022). "Epigenetic regulation of MALAT1 in osteosarcoma has been investigated especially with respect to the expression pattern of EZH2." (PMID 35755302, 2022). "In conclusion, Circ_ANKIB1 binds miR-26b-5p and modulates EZH2 to accelerate the chemo-resistance of osteosarcoma." (PMID 35264070, 2022). "The oncogenic lncRNA MIR100HG is another potential prognostic marker that promotes osteosarcoma progression via interacting with EZH2." (PMID 35755302, 2022). "Similar to what was described for Ewing sarcoma, the abrogation of EZH2 expression in osteosarcoma cells was able to decrease cellular growth, migration, invasion and clonogenicity." (PMID 34198693, 2021). "In accordance with this, mRNA levels for EZH2 significantly increased in those osteosarcoma patients who developed metastasis within 5 years after the initial diagnosis." (PMID 34198693, 2021). "In osteosarcoma cells, MIR100HG promotes proliferation by interacting with the EZH2 protein of the polycomb repressor complex-2, causing repression of LATS1/2, mediators of Hippo signaling." (PMID 33941855, 2021). "The potential synergistic function between oncogene BCL6 and EZH2 in osteosarcoma requires further investigation." (PMID 31903129, 2020). "The present findings indicate that lincFOXF1 is involved in the progression of osteosarcoma through binding with EZH2, further regulating GIT1 expression." (PMID 32945076, 2020). "Collectively, these findings indicate that lincFOXF1 physically interacts with EZH2 and EZH2 is required for lincFOXF1 medullated inhibition phenotypes which are involved in the metastasis of osteosarcoma cells." (PMID 32945076, 2020). "LncRNA-ANCR was first shown to regulate cell growth of osteosarcoma by interacting with EZH2 and subsequently affecting the expression of p21 and p2721." (PMID 31534128, 2019). "The data set GSE39262 showed that the expression level of EZH2 mRNA in LMS was higher than that in osteosarcoma, fibrosarcom and Ewing sarcoma (p < 0.05)." (PMID 30120321, 2018). "Although the clinical significance of H3K27me3 and PRC2 expression in OS needs to be further investigated by using a large cohort of cases, high EZH2 gene expression appeared to be correlated with a poor outcome in osteosarcoma." (PMID 29930752, 2018).
osteosarcoma (continued). "Our data indicated that, in osteosarcoma cells, EZH2 is a direct target of miR-138, where EZH2 expression is negatively correlated with that of miR-138 in osteosarcoma." (PMID 27019355, 2016). "Consistent with the results of the osteosarcoma TMA, EZH2 protein expression was mainly localized in the nucleus of osteosarcoma cells." (PMID 27223261, 2016). "Similar results were observed in osteosarcoma cells treated with EZH2 specific inhibitor 3-deazaneplanocin A (DZNep), which exhausted cellular levels of EZH2." (PMID 27223261, 2016). "As far as we know, the present study is the first to propose the miR-138/EZH2 chemoresistance axis in osteosarcoma." (PMID 27019355, 2016). "First, we focused solely on miR-138 regulation of EZH2, and future studies should explore the role of the up/downstream miR-138/EZH2 signaling pathway to describe a better interpretation of the role of this pathway in osteosarcoma." (PMID 27019355, 2016). "In conclusion, this study demonstrates that miR-138 acts as a tumor suppressor in osteosarcoma, inhibiting cell proliferation, migration, and invasion by downregulating EZH2 expression." (PMID 27019355, 2016). "In our current osteosarcoma model, we also found that DZNep reduces EZH2 at the protein level and subsequently decreases H3K27me3." (PMID 27223261, 2016). "We found reduced expressions of MT1-MMP, MMP-2, and MMP-7 after EZH2 knockdown in osteosarcoma cells." (PMID 27223261, 2016). "We confirmed that miR-138 enhances osteosarcoma cell chemosensitivity by directly targeting EZH2 and that EZH2 overexpression reverses the miR-138–dependent chemosensitivity, which identifies a new direction for chemotherapy." (PMID 27019355, 2016). "To investigate the functional role of EZH2 in osteosarcoma, we used synthetic RNA interference (RNAi) to disrupt EZH2 expression in two osteosarcoma cells lines in vitro." (PMID 27223261, 2016). "Rescue experiments were performed to further validate that EZH2, as a target gene, is involved in the miR-138–induced anti-tumor process in osteosarcoma cells." (PMID 27019355, 2016). "Western blot revealed constitutive EZH2 expression in all four osteosarcoma cell lines (KHOS, U2OS, SAOS, and MG63) examined; whereas there was no expression in osteoblast cells (NHOST, HOBC)." (PMID 27223261, 2016). "Our findings indicate that EZH2 functions as a key coordinator involved in apoptosis signaling in osteosarcoma." (PMID 27223261, 2016). "By Kaplan-Meier analysis, we present the first study to examine the prognostic value of EZH2 expression in osteosarcoma patients using high-throughput tissue microarray analysis." (PMID 27223261, 2016). "Third, we found that EZH2 was a direct target of miR-138 and that forced EZH2 expression restored the inhibitory effects of miR-138 in osteosarcoma." (PMID 27019355, 2016). "Immunoflurescent staining showed that EZH2 protein is also localized in the nucleus of osteosarcoma cells, which is consistent with the immunohistochemistry staining of EZH2 in osteosarcoma tissues." (PMID 27223261, 2016). "To examine the role of EZH2 in osteosarcoma cell growth and proliferation, we used RNAi to disrupt EZH2 expression in osteosarcoma cells in vitro." (PMID 27223261, 2016). "The wound healing assay was also carried out to validate the effects of EZH2 silencing on osteosarcoma cell migration." (PMID 27223261, 2016). "The immunohistochemistry staining results showed that EZH2 protein expression is mainly detected in the nucleus of osteosarcoma cells." (PMID 27223261, 2016). "EZH2 significantly attenuated the inhibition of osteosarcoma cell proliferation, migration, and invasion induced by miR-138 overexpression." (PMID 27019355, 2016). "In this study, we performed immunohistochemistry to evaluate the significance of EZH2 expression in tumor tissues from 64 osteosarcoma patients." (PMID 27223261, 2016). "We subsequently investigated the functional and therapeutic relevance of EZH2 as a target in osteosarcoma." (PMID 27223261, 2016).